PLOD3 (procollagen-lysine,2-oxoglutarate 5-dioxygenase 3)
Diseases named in the same sentence as PLOD3 in open-access papers (continued):
Sharing a sentence is not in itself a finding about the gene and the disease.
cancer (continued). "Analyzing the genetic alteration of PLOD3 in our study, it is observable that the mutation and CNA contribute, to a great extent, to diverse cancers." (PMID 34576068, 2021). "A number of studies have demonstrated that overexpression of PLOD2 and PLOD3 promotes cancer progression and metastasis." (PMID 31199049, 2019). "Many studies demonstrate that increased PLOD2 and PLOD3 expression is required for cancer progression and metastasis." (PMID 30003082, 2018). "Procollagen-lysine, 2-oxoglutarate 5-dioxygenase 3 (PLOD3) modulates cancer progression and metastasis." (PMID 29644003, 2018). "PLOD1, PLOD2, and PLOD3 levels were upregulated in most cancers." (PMID 39068670, 2024). "PLOD3 was up-regulated in some types of cancers and promoted tumor malignant progression." (PMID 35752862, 2022). "In addition, we also investigated the relation of PLOD3 expression to the tumor mutational burden (TMB) and microsatellite instability (MSI), respectively, in different cancers from the TCGA database." (PMID 34576068, 2021). "Furthermore, a gene enrichment analysis was carried out, to reveal the potential significance of PLOD3 gene regulation in cancer." (PMID 34576068, 2021). "PLOD3 expression was analyzed using The Cancer Genome Atlas (TCGA) pan-cancer data." (PMID 34646265, 2021). "In future research, we suggest exploring whether PLOD3 expression relates to the sensitivity of therapeutic interventions, such as radio-, immuno- and chemotherapy across various types of cancers." (PMID 34576068, 2021). "PLOD3 expression negatively correlated with survival periods and the infiltration level of CD8+ T cells, but positively correlated to the infiltration of cancer associated fibroblasts in diverse cancers." (PMID 34576068, 2021). "We thus conclude that the ADAM12, MMP1, SERPINE1, PLOD3, and P4HA3 signature showed a close association with a pan‐cancer effect on prognosis and is related to ECM proteins in the TME which corresponding with immunologically “cold” cancer types." (PMID 34121340, 2021). "The Notch signaling pathway is activated in CRC and other cancer types and could be related to poor-prognosis subtypes and metastasis in CRC, which may explain the association of PLOD3 with poor prognosis." (PMID 34646265, 2021). "In the 18 cancer types from TCGA, we calculated tissues with mutations of ADAM12, MMP1, SERPINE1, PLOD3, and P4HA3, and they had limited mutations, and their mutation sites had few significant effects on gene expression or function gain across the 18 cancer types." (PMID 34121340, 2021). "The CNA of PLOD3 occurred in all of these cancers except KICH, THYM and UVM." (PMID 34576068, 2021). "PLOD3 acts as an inducer of various cancers, and it could be a potential biomarker for prognosis and targeted treatment." (PMID 34576068, 2021). "Data mining using TCGA datasets showed that PLOD3 was overexpressed in 19 types of tumor tissues compared with normal tissues, indicating that PLOD3 may serve as a novel biomarker in cancer." (PMID 34646265, 2021). "Based on these facts, we focused on cancer cell survival with respect to PLOD3 function." (PMID 30770789, 2019). "The combinatorial treatment attenuated cell viability and increased cell death compared to cisplatin alone, suggesting that PLOD3 status might influence the chemosensitivity of cancer cells to cisplatin." (PMID 30770789, 2019). "Also, immunohistochemical staining showed that overexpressed PLOD2 and PLOD3 were detected in cancer lesions." (PMID 31199049, 2019). "Considering the previously established role of STAT3 in cancer metastasis, we hypothesized that PLOD3 promotes metastasis in a STAT3-dependent manner in the model system used herein." (PMID 30442941, 2018). "However, we observed that the N-glycopeptides of several cancer-associated proteins (e.g., EGFR, LGALS3BP, and PLOD3) were down-regulated in hiPSCs compared to hESCs." (PMID 27808266, 2016). "In addition, PLOD3 expression was markedly increased in 17 cancer types." (PMID 35265665, 2021).
cancer (continued). "As genome instability is a hallmark of cancer, PLOD3 was expressed higher in COAD samples with high chromosomal instability (CIN-high) than those with low CIN (CIN-low) and higher in those with low MSI than high MSI, indicating that PLOD3 expression was associated with tumor genomic instability." (PMID 34239923, 2021). "However, using the PLOD gene family and PLOD3 protein expression might be a valuable marker for cancer prognosis." (PMID 34576068, 2021). "Hence, we may identify PLOD3 as a prognostic biomarker and a potential therapeutic target for some cancers, in an attempt to improve survival probability." (PMID 34576068, 2021). "Next, we examined whether PLOD3 status influences the chemosensitivity of cancer cells." (PMID 30770789, 2019). "Hence, the present study aimed to test the hypothesis that targeting of STAT3 enables cancer suppression at multiple levels via attenuation of the oncogenic potential of PLOD3 owing to upstream and downstream aberrations in cancer metastasis pathways." (PMID 30442941, 2018). "The most predominant ECM regulators, ADAM12, MMP1, SERPINE1, PLOD3, and P4HA3, have been classified as a five‐gene signature that produces a broad effect over 29 types of cancer." (PMID 34121340, 2021). "Our immunohistochemical analysis of various cancer tissues revealed glial cells and CAF as the main cellular population expressing PLOD3." (PMID 34576068, 2021). "As a result, the higher protein expression levels of ADAM12, PLOD3, P4HA3, and SERPINE1 were detected in multiple types of cancer compared with the normal tissue specimens, which was consistent with their mRNA expression patterns." (PMID 34121340, 2021). "This study shows that PLOD3 expression was negatively correlated to the infiltration degree of CD8+ T cells, but was positively related to CAFs in the following cancers, SKCM, LUSC and THCA." (PMID 34576068, 2021). "Further analysis of differences in the gene expression levels of ADAM12, MMP1, SERPINE1, PLOD3, and P4HA3 between tumor and adjacent normal tissues in 18 cancer types from TCGA were examined." (PMID 34121340, 2021). "In general, the mRNA expression levels of ADAM12, MMP1, SERPINE1, PLOD3, and P4HA3 were correlated with immune infiltration score and macrophages and dendritic cells (DCs) in most types of cancer." (PMID 34121340, 2021). "The ECM‐receptor interaction gene set was further analyzed for correlation with ADAM12, MMP1, SERPINE1, PLOD3, and P4HA3 in the 29 cancer types." (PMID 34121340, 2021). "Since the client protein and function of PLOD1, PLOD2, and PLOD3 in collagen synthesis are different, it is important to develop specific inhibitors for PLOD to halt cancer progression." (PMID 30003082, 2018). "Although PLOD3 has been evaluated in a variety of cancers, its role in CRC cancers is unclear." (PMID 38184566, 2024). "The protein expression levels of PLOD3 and P4HA3 were high in most cancer tissues." (PMID 34121340, 2021). "Moreover, PLOD3 and COL12A1 were related to the epithelial–mesenchymal transition (EMT) pathway, which is regarded as one of the core events that contribute to cancer metastasis." (PMID 34585630, 2021). "The coefficient of PLOD3 made a greater contribution than the other ten ECM regulator genes using the least absolute shrinkage and selection operator (LASSO) Cox regression model in the 18 cancer types." (PMID 34121340, 2021). "This could be corroborated by our proteomics functional analysis, where we found, for instance, a higher abundance of HADH, PLOD3 and ACAT1 (lysine degradation) and PFKL, NTRK1, PDHB and PDHA1 (central carbon metabolism in cancer) in control piglets compared to UL." (PMID 38409238, 2024). "Taken together, our findings elucidate that PLOD3 could act as an inducer of various cancers, PLOD3 expression possessed a negative correlation with the survival odds and the infiltration level of CAF and a negative relation to the CD8+ T cells infiltration, to a certain extent." (PMID 34576068, 2021).
cancer (continued). "Additionally, the expression of PLOD3 was related to pathological stages in ACC, KICH, KIRC, LIHC and SKCM, but not significantly related to the stages of other cancers." (PMID 34576068, 2021).
tumor (31 papers, 2010 to 2025). "Two GEO datasets (GSE74602 and GSE113513) were used to validate the diagnostic value of PLOD3 using paired tumor and normal samples." (PMID 34646265, 2021). "The PLOD3 gene is critical for collagen synthesis, thus, mutations are related with disorders of the connective tissue and the development of several tumor entities." (PMID 34576068, 2021). "As high immune cell infiltration was associated with high tumor burden and PLOD3 was associated with tumor genome instability, we then investigated the association of PLOD3 expression with immune cell infiltration." (PMID 34239923, 2021). "Thus far, the mechanisms underlying tumor cell migration and invasion involving PLOD3 have been unknown." (PMID 30442941, 2018). "PLOD3 knockdown suppressed tumor proliferation and enhanced tumor apoptosis; in contrast, upregulation of PLOD3 facilitated tumor proliferation and dampened tumor apoptosis." (PMID 40133271, 2025). "The results indicated that the level of PLOD3 in the serum of CRC patients was significantly higher than that in the serum of healthy individuals, moreover, III + IV tumor stage group showed higher PLOD3 concentration in serum." (PMID 40133271, 2025). "PLOD3 overexpression significantly increased tumor growth, as reflected by an obvious increase in tumor weight and volume compared with those in the control group." (PMID 40133271, 2025). "Our study also clarified the potential link between PLOD3 and the TNFα/NF-κB signaling pathway in the tumor microenvironment." (PMID 38184566, 2024). "Further studies showed that PLOD3 facilitated the T cell activation in the tumor microenvironment and affected the TNF-α/ NF-κB pathway." (PMID 38184566, 2024). "The western blot and RT-qPCR analysis further confirmed that CRC tumor tissues and cell lines show a higher PLOD3 expression than the matched normal tissues or colon cell line." (PMID 38184566, 2024). "We observed that when we knocked down PLOD3, the infiltration of cytotoxic T cells in the tumor microenvironment was significantly increased." (PMID 38184566, 2024). "Stable knockdown of PLOD3 also significantly inhibited liver metastasis of CRC cells in different xenografts models, while stable overexpression of PLOD3 promotes liver metastasis and tumor progression." (PMID 38184566, 2024). "Second, PLOD3 depletion led to significantly decreased tumor growth in the mice, validating the critical role of PLOD3 in mediating Trastuzumab resistance." (PMID 35835735, 2022). "Existing research shows that elevated expression levels of PLOD3 can accelerate tumor progression and indicate poor prognosis, which is consistent with our signature where the weight of PLOD3 was positive." (PMID 35788194, 2022). "We noticed that knockdown of PLOD3 significantly suppressed cell viability, reduced migration and invasiveness of tumor cells." (PMID 35835735, 2022). "Not only do our results discover upregulated expression of POLD3 in GC cell lines, GC xenograft models and clinical tumor tissue, but also link PLOD3 expression with poor survival outcomes in GC patients." (PMID 35835735, 2022). "Motivated by our in vitro findings, we aimed to determine the effect of PLOD3 on mediating Trastuzumab resistant GC tumor growth in vivo." (PMID 35835735, 2022). "PLOD1, PLOD2, and PLOD3 were highly expressed in LGG tumor tissues compared to normal tissues (p < 0.01)." (PMID 35250490, 2022). "The comparison of the tumor samples with distinct TNM stages revealed that PLOD3 was increased in the advanced TNM stages in both TCGA and CPTAC cohorts (P value <0.01)." (PMID 34239923, 2021). "In particular, PLOD3 expression appears to have a tumor immunological effect, and is related to multiple immune cells." (PMID 34576068, 2021). "The results showed that PLOD3 expression differed significantly according to tumor N stage, M stage, clinical stage, and microsatellite instability (MSI) status." (PMID 34646265, 2021).
tumor (continued). "We next evaluated the correlation between PLOD3 and survival, clinical stage and the tumor microenvironment (TME) of CRC based on public databases." (PMID 34585630, 2021). "The 100 most highly correlated genes with PLOD3 were selected and the expression of the top five was examined for 33 tumor entities." (PMID 34576068, 2021). "PLOD3 mRNA was also up-regulated in GC tissues and cell lines, which was significantly correlated with larger tumor size and poor patient prognosis." (PMID 31892979, 2020). "In this study, we designed human PLOD3-specific short interfering (si)RNAs and tested their effects on tumor growth inhibition in vitro and in vivo." (PMID 30770789, 2019). "The most pronounced tumor growth-inhibitory effect (60%) was observed in the PLOD3 siRNA plus irradiation group." (PMID 30770789, 2019). "Tumor volumes were markedly decreased by more than ~36% and 47%, compared to those in the control siRNA group, in the PLOD3 siRNA-treated group and radiation-treated group, respectively." (PMID 30770789, 2019). "Tumor growth statistically decreased with PLOD3 silencing compared with the GBM8401-iRL mock and shScramble group." (PMID 29644003, 2018). "PLOD3 silencing reduced the incidence of lung metastasis by decreasing the number of nodules and tumor nodule volume (siControl (siCON)—5.8 mm3 vs siPLOD3—0.53 mm3)." (PMID 30442941, 2018). "Notably, elevated PLOD3 expression is positively correlated with nervous system invasion, tumor stage, lymph node metastasis, and distant metastasis in CRC patients." (PMID 40133271, 2025). "Additionally, the length of the colon in the control group was reduced, however, the number and the size of the tumor in the PLOD3 knockdown group is significant decreased." (PMID 40133271, 2025). "Interestingly, the expression profile of PLOD3 was found to be positively correlated with nervous invasion, tumor stage, lymph node metastasis, and distant metastasis in CRC patients." (PMID 40133271, 2025). "Therefore, most immune cells' infiltration in tumor immune activation is elevated in the low-expression PLOD3 group." (PMID 38184566, 2024). "PLOD3 expression was positively related with age and tumor grade." (PMID 39068670, 2024). "PLOD3 expression was positively correlated with age (P = 0.006977) and tumor grade (P = 0.0004829)." (PMID 39068670, 2024). "The PLOD family members (PLOD1, PLOD2, and PLOD3) were overexpressed in HNSCC tumor tissue." (PMID 36820030, 2023). "These evaluations indicated that PLOD1, PLOD2, and PLOD3 might be high expressed in HNSCC tumor tissues compared with normal tissues (all p < 0.01)." (PMID 36820030, 2023). "Furthermore, analysis of biopsies for potential proteomic predictive biomarkers of response showed that patients with lower levels of PML or PLOD3 in tumor had more favorable clinical outcomes." (PMID 35641481, 2022). "Patients with lower tumor PML or PLOD3 expression had favorable ORR and PFS." (PMID 35641481, 2022). "Hence, we found that not only PLOD1 but also PLOD2 and PLOD3 were abundantly expressed in tumor tissues." (PMID 35250490, 2022). "We further explored the correlation between PLOD3 and tumor infiltrating immune cells." (PMID 34585630, 2021). "Furthermore, we stratified the tumor samples into two groups by the PLOD3 expression (high vs. low)." (PMID 34239923, 2021). "PLOD3 expression was significantly higher in tumor than in normal samples." (PMID 34646265, 2021). "PLOD3 was expressed higher in COAD samples with high chromosomal instability (CIN-high) than those with low CIN (CIN-low) and higher in those with low MSI than high MSI, indicating that PLOD3 expression was associated with tumor genomic instability." (PMID 34239923, 2021). "As modification of collagen and the extracellular matrix is related to tumor invasion and angiogenesis, PLOD3 may be involved in tumor development." (PMID 35265665, 2021). "High and low PLOD3 expression and tumor prognosis was compared." (PMID 34576068, 2021).